SPEF2 (sperm flagellar and cilia associated 2)
Description:
Required for correct axoneme development in spermatozoa. Important for normal development of the manchette and sperm head morphology. Essential for male fertility. Plays a role in localization of the intraflagellar transport protein IFT20 to the manchette, suggesting function as an adapter for dynein-mediated protein transport during spermatogenesis. Plays a role in bone growth where it seems to be required for normal osteoblast differentiation (By similarity). Required for normal beat frequency of tracheal epithelial cilia and oviduct cilia (By similarity).
Synonyms: KPL2; FLJ23577; CT122; SPGF43
Tractability: Antibody: its Gene Ontology location is reachable by antibodies, with medium confidence. PROTAC: ubiquitination databases record sites on it.
Gene: Protein-coding gene on chromosome 5 (35,617,844 to 35,814,611, forward strand). Ensembl gene ENSG00000152582.
Subcellular location: Cell projection, cilium, flagellum; Cytoplasm, cytoskeleton, flagellum basal body; Cytoplasm; Cytoplasm, cytoskeleton; Golgi apparatus; Cytoplasm, cytoskeleton, cilium axoneme
Subcellular location (Human Protein Atlas): Flagellar centriole; Primary cilium; Cytosol; Mid piece; Nuclear bodies
Gene Ontology:
Biological process: sperm axoneme assembly; brain morphogenesis; epithelial cilium movement involved in extracellular fluid movement; respiratory system development; skeletal system morphogenesis; spermatogenesis
Cellular component: cilium; sperm flagellum; cytoplasm; Golgi apparatus; manchette; sperm midpiece; axoneme; cytoskeleton; extracellular region; motile cilium
Genetic constraint (gnomAD): Loss-of-function variants: 150 observed, 186.12 expected, observed/expected ratio (o/e) 0.81, 90% interval 0.7 to 0.92. The upper end of that interval is the gene's LOEUF score, 0.92, which puts it in group 3 of 6, group 1 being the genes least tolerant of losing a copy. Missense variants: 1,889 observed, 1,948.3 expected, observed/expected ratio (o/e) 0.97, 90% interval 0.93 to 1.01. Synonymous variants: 637 observed, 655.23 expected, observed/expected ratio (o/e) 0.97, 90% interval 0.91 to 1.04.
Gene-disease validity (ClinGen):
ClinGen rates the evidence that SPEF2 causes each of these diseases.
primary ciliary dyskinesia (autosomal recessive): Definitive. A rare, genetically heterogeneous, primarily respiratory disorder characterized by chronic upper and lower respiratory tract disease.
Homologues: Orthologues: macaque SPEF2 (96% identical), chimpanzee SPEF2 (85% identical), dog SPEF2 (70% identical), pig SPEF2 (70% identical), rabbit SPEF2 (70% identical), rat Spef2 (60% identical), mouse Spef2 (60% identical), zebrafish spef2 (34% identical), tropical clawed frog spef2 (30% identical).
Diseases named in the same sentence as SPEF2 in open-access papers:
SPEF2 is named in the same sentence as 22 diseases in open-access papers, as found by Europe PMC text mining. Sharing a sentence is not in itself a finding about the gene and the disease. The quoted sentences say what the papers report.
male infertility (9 papers, 2013 to 2025). The inability of the male to effect fertilization of an ovum after a specified period of unprotected intercourse. "Sperm flagellar protein 2 (SPEF2) is essential for motile cilia, and lack of SPEF2 function causes male infertility and primary ciliary dyskinesia." (PMID 29339787, 2018). "Thus, IF microscopy in sperm flagella with antibodies targeting SPEF2 can help to determine pathogenicity of DNA variants in HYDIN- and SPEF2-mutant individuals, aiding diagnosis of male infertility." (PMID 36873931, 2023). "SPEF2-mutant individuals SP-24 and SP-32 presented with male infertility and did not have a prior diagnosis of any chronic airway disease." (PMID 36873931, 2023). "We and others have reported male infertility in HYDIN-and SPEF2-mutant individuals." (PMID 36873931, 2023). "Mutations in SPEF2 have been reported to cause MMAF with or without primary ciliary dyskinesia (PCD) symptoms, indicating that its loss-of-function mutations lead to spermatogenic dysfunction and male infertility." (PMID 37174638, 2023).
primary ciliary dyskinesia (8 papers, 2013 to 2023). "The loss of SPEF2 in mice resulted in spermatogenesis defects and primary ciliary dyskinesia, which decreased the number of elongating spermatids and disrupted the formation of the sperm tail." (PMID 35145544, 2021). "The loss of SPEF2 function in mice results in spermatogenesis defects and primary ciliary dyskinesia." (PMID 33414812, 2020).
Hydrocephalus (7 papers, 2012 to 2025). Hydrocephalus is an active distension of the ventricular system of the brain resulting from inadequate passage of CSF from its point of production within the cerebral ventricles to its point of absorption into the systemic circulation. "The hydrocephalus was present in mice with 129 and B6 background indicating that Spef2 is a causative gene for PCD29,32." (PMID 29339787, 2018). "Although we cannot rule out the possibility that some of the growth defects originate as secondary effects of severe PCD symptoms such as hydrocephalus, several findings suggest that SPEF2 is directly involved in the regulation of bone formation." (PMID 29339787, 2018). "The analysis of a Spef2 knockout (KO) mouse model revealed hydrocephalus, growth retardation and death prior to five weeks of age." (PMID 29339787, 2018). "Spef2 KO mice suffered from severe hydrocephalus and mice survived a maximum of five weeks." (PMID 29339787, 2018). "However, since the hydrocephalus was more severe at P31, it may explain the more profound difference between WT and Spef2 KO at P31 compared to P15." (PMID 29339787, 2018). "We previously demonstrated that mouse models of PCD lacking ciliary proteins CFAP221, CFAP54 and SPEF2 all have hydrocephalus with a strain-dependent severity." (PMID 30190587, 2018). "The role played by the genetic background for manifestation of hydrocephalus was previously demonstrated in mouse models of PCD lacking ciliary proteins CFAP221, CFAP54 and SPEF2, respectively." (PMID 31383820, 2019).
Infertility (3 papers, 2019 to 2023). "We found that the structure of the gonads and sperm were greatly deformed, and we identified several promising genes related to spermatogenesis and infertility, such as SPEF2, DNAI1, and TACR3, through RNA-seq." (PMID 36617567, 2023). "We identified ten infertile male individuals with pathogenic variants in CCDC39 (one) and CCDC40 (two) encoding ruler proteins, RSPH1 (two) and RSPH9 (one) encoding radial spoke head proteins, and HYDIN (two) and SPEF2 (two) encoding CP-associated proteins, respectively." (PMID 36873931, 2023). "Furthermore, we found that fadrozole permanently influenced the differentiation of secondary sexual characteristics and reproductive tissues, and we identified several candidate genes, such as SPEF2, DNAI1, and TACR3, that were related to infertility in sex-reversed chickens." (PMID 36617567, 2023).
pancreatitis (2 papers, 2017 to 2019). Inflammation of the pancreas. "Accordingly, G allele carriers of the rs11556218 SNP in the IL16 gene and carriers of the A allele in the rs34708521 SNP of the SPEF2 gene, were at higher risk of pancreatitis in both discovery and replication cohorts." (PMID 28574850, 2017). "Furthermore, the analysis in the context of a larger sample size provided by the combined cohort further supports the correlation between the SNPs in MYBBP1A, IL16 and SPEF2 with pancreatitis as the associations gained more significance in the pooled sample." (PMID 28574850, 2017). "Furthermore, rs11556218 in IL16 and rs34708521 in SPEF2 were both associated with thrombosis (p=0.01 and p=0.03, respectively) and pancreatitis (p=0.02)." (PMID 28574850, 2017). "In an attempt to increase the discrimination ability of the model, rs11556218 in IL16 and rs34708521 in SPEF2 that were initially investigated for their association with thrombosis but later found to be also associated with pancreatitis, were added to the analysis." (PMID 28574850, 2017). "The association of SNPs in MYBBP1A, SPEF2 and IL16 geneswith pancreatitis was replicated in the validation cohort (p ≤0.05) as well as in combined cohort (p=0.0003, p=0.008 and p=0.02, respectively)." (PMID 28574850, 2017). "Interestingly, rs3809849 in the MYBBP1A gene was associated with allergy, pancreatitis, thrombosis, event-free survival (EFS) and overall survival, while rs11556218 in IL16 gene and rs34708521 in SPEF2 gene were both associated with thrombosis and pancreatitis." (PMID 35582721, 2019).
thrombosis (2 papers, 2017 to 2019). "In the multivariate analysis, only the association of rs34708521 in SPEF2 gene with thrombosis lost significance (OR = 4.3; 95% CI, 0.8-22.3; p = 0.08), whereas other associations remained significant in their respective models." (PMID 28574850, 2017).
diffuse large B-cell lymphoma (1 paper, 2025). "CircSPEF2, which is generated by the reverse splicing of SPEF2, is lowly expressed in diffuse large B-cell lymphoma and affects its progression through the circSPEF2-miR-16-5p-BACH2 axis." (PMID 41217541, 2025).
skin cancer (1 paper, 2020). "In addition to the mutations in genes known to be associated with skin cancer development, we identified multiple new UV target genes that harbor high frequency of T > C conversions, including GVINP1, NCF1B, FLG2, and SPEF2." (PMID 32188867, 2020).
Xeroderma pigmentosum complementation group A (1 paper, 2019). Xeroderma pigmentosum complementation group A (XPA) is a severe form of xeroderma pigmentosum (XP; see this term), a rare photodermatosis predisposing to skin cancers. "These eQTLs are significantly associated with 4 genes, including ADGRB2 (adhesion G protein-coupled receptor B2), WASF3 (WAS protein family member 3), SPEF2 (sperm flagellar 2), and XPA (xeroderma pigmentosum complementation group A)." (PMID 31039743, 2019).
tumor (3 papers, 2021 to 2025). "Conversely, patients with high SPEF2 expression and a high tumor mutational burden exhibited shorter OS (p=0.0023, Hazard ratio [HR]: 2.17, 95% CI: 1.3 – 3.62), (data not shown)." (PMID 40747466, 2025). "Among them, GABBR2 and TUFT1 exhibited high expression levels in tumor tissues, whereas SPEF2 demonstrated low expression." (PMID 41217541, 2025). "The study also identified other genes with significant association within at least one tumor type or breed, including ASPM, which functions in the mitotic spindle, and SPEF2 and FSIP2, both related to spermatogenesis." (PMID 34344882, 2021).
infection (2 papers, 2013 to 2022). The state of being infected such as from the introduction of a foreign agent such as serum, vaccine, antigenic substance or organism. "The SPEF2 expression in the infection group was significantly higher than that in the control group at 24 h (P < 0.01)." (PMID 34998433, 2022). "Differences in the severity of response to infection in the nm1054 and bgh mutants may be due to differences in Pcdp1 and Spef2 protein function that could have differential effects on mucociliary clearance." (PMID 24360193, 2013). "After infection with ALV-J, PRLR and SPEF2 expression in DF-1 cells was evaluated." (PMID 34998433, 2022).
cancer (1 paper, 2025). A tumor composed of atypical neoplastic, often pleomorphic cells that invade other tissues. "This study investigated the expression of cancer-testis antigens SPEF1 and SPEF2 in BLCA using comprehensive bioinformatic analyses to assess their potential as biomarkers." (PMID 40747466, 2025). "The current study was the first of its kind to explore the potential clinical role of SPEF1 and SPEF2 in BLCA, building upon previous research that identified these proteins in other cancers and potentially premalignant lesions." (PMID 40747466, 2025).
SPEF2 also shares sentences with these, for which no sentence is quoted: lung disease (2 papers); Allergy (1); bladder cancer (1); chronic lung disease (1); congenital hydrocephalus (1); deafness (1); nasopharyngeal carcinoma (1); respiratory disease (1); Streptococcus pneumoniae infection (1); Usher syndrome (1).